AURKA (aurora kinase A)
Diseases named in the same sentence as AURKA in open-access papers (continued):
Sharing a sentence is not in itself a finding about the gene and the disease.
cancer (continued). "Besides, recent studies have mentioned that AURKA probably takes part in cancer development and progression as well as tumorigenesis." (PMID 34337875, 2021). "Although the high level of AURKA could be approved as a biomarker, it might make cancer patients show poor survival." (PMID 34337875, 2021). "AURKA has been confirmed as an oncogene in cancer development." (PMID 34149795, 2021). "AURKA plays multiple roles in regulating cancer development, while its oncogenic roles might vary in different types of cancer." (PMID 34257537, 2021). "Furthermore, alterations in the associated genes (CDK-1, CDK-4, CCNE1, CDKN2A, RBI, NCAPG, AURKA, and CCND2) were determined in five CRC studies (CRC, TCGA, Firehose, CRC, TCGA, Nature, CRC, Pan-Cancer, MSKCC and CPTAC-2)." (PMID 33732631, 2021). "As a result, AURKA could be an attractive target for cancer therapy, and multiple inhibitors have been developed." (PMID 34337035, 2021). "Since the overexpression of AURKA could stop apoptosis, and promote cancer cell proliferation, the AURKA inhibitors (AKIs) have the ability to inhibit the expression of this gene so that the cancer cell would cease to spread and migrate." (PMID 34337875, 2021). "In this review, we highlight the importance of AURKA in cancer cell signal transduction." (PMID 33451333, 2021). "In silico virtual screening and molecular docking were performed to predict probable ligands interacting with AURKA, which may provide potential drug candidates as promising AURKA inhibitors in cancer therapy." (PMID 32978717, 2021). "Therefore, this corroborates the existence of a metabolic switch upon the overexpression of AURKA, and it further reinforces the link between the efficiency of mitophagy and the metabolic capacity of cancer cells." (PMID 33820826, 2021). "Since the AURKA participates in the cell cycle and some signaling pathways in normal cells, the aberrant level of this gene can play an important role in many types of cancers." (PMID 34337875, 2021). "Previous studies have confirmed that AURKA is related to the prognosis of a variety of cancers (breast, colorectal, pancreatic, gastric, and head and neck) and may be a therapeutic target." (PMID 34917126, 2021). "This approach identified many confirmed targets with existing drugs that are currently used in the clinic or are in various stages of clinical trials in other cancers (for example clinical trials for drugs targeting AURKA and BRD4), emphasizing the efficacy of our approach." (PMID 34154646, 2021). "As cancer-associated kinases, both AURKA and AURKB have been extensively studied in search for new potential small molecular inhibitors that could be used in anti-cancer therapy (reviewed by Borisa and Bhatt)." (PMID 33572108, 2021). "Although deactivating tumor suppressors is a part of usual AURKA duties, it could raise cancer cells by permitting them to evade apoptosis." (PMID 34337875, 2021). "AURKA overexpression can promote cell cycle progression even when DNA is damaged or chromosomal segregation is abnormal, resulting in genomic and chromosomal instabilities, which are hallmarks of malignant tumors." (PMID 34050264, 2021). "Many studies have shown that the AURKA gene has an oncogenic role in some cancers, but its expression in some cancers remains unknown." (PMID 34337875, 2021). "In addition to the cancer stem cell inhibitors, clinical trials are ongoing with multiple N-Myc, AURKA and BET inhibitors and EZH2 inhibitors (clinicaltrials.gov (accessed on 18 December 2020))." (PMID 33572108, 2021). "HDAC inhibitors have been shown to repress the expression of AURKA in various cancer cells, and AKIs can decrease the activity of HDAC proteins, suggesting that synergetic effects could be obtained by combining AKIs and HDAC inhibitors." (PMID 33451333, 2021).
cancer (continued). "Aurora kinase A, which its role in mitotic progression has been extensively characterized, was shown to be located and imported into the mitochondrion in several human cancer cell lines, and to have an impact on mitochondrial dynamics and energy production." (PMID 33547867, 2021). "Yet, the consequences of AURKA overexpression on mitochondria as a potential cancer-promoting event are still fairly unknown." (PMID 33820826, 2021). "The expression level of AURKA could be utilized in many cancers as a biomarker that might detect some cancers at the beginning levels." (PMID 34337875, 2021). "Eventually, GEO data showed that JQ1, actinomycin D1, and camptothecin could reduce the expression of AURKA gene in different cancer cell lines (logFC < 1, p < 0.01)." (PMID 34337875, 2021). "Actinomycin D1 and camptothecin could reduce the expression of AURKA gene in different cancer cell lines based on GEO data." (PMID 34337875, 2021). "AURKA overexpression can also inhibit ferroptosis of cancer cells by inhibiting GPX4." (PMID 34616431, 2021). "Moreover, we provide a summary of the selective inhibitors and pan-inhibitors of AURKA tested in various preclinical and clinical studies for the treatment of cancer." (PMID 33451333, 2021). "Eventually, our outcomes showed that some drugs might be able to lower the level of AURKA in various cancers." (PMID 34337875, 2021). "Our findings mentioned that these drugs could be good candidates to lower the expression level of the AURKA gene in various cancer samples." (PMID 34337875, 2021). "Increased expression of AURKA, the Aurora kinase involved in the regulation of the cell cycle progression, may cause CIN in a variety of cancers." (PMID 34204115, 2021). "This study also indicated the critical role of AURKA rs8173 in cancer modification." (PMID 35201446, 2021). "In addition to the effects in the cancer environment, AURKA actively promotes DNA repair and acts as a transcription factor to promote cell migration and invasion." (PMID 34556750, 2021). "Nevertheless, the molecular mechanisms by which aberrant AURKA activity induces cancer cell plasticity, chemoresistance, and progression in TNBCs are largely unknown." (PMID 33674749, 2021). "To date, dozens of small molecule AURKA-specific inhibitors or pan-aurora kinase inhibitors have been developed, and 11 of these inhibitors have been evaluated in at least one complete clinical trial for patients with cancer." (PMID 34050264, 2021). "Besides, AURKA promoted cancer metastasis by regulating epithelial-mesenchymal transition and cancer stem cell properties in HCC." (PMID 33552715, 2021). "In several cancer cell lines, AURKA reportedly has several non‐mitotic functions." (PMID 34704342, 2021). "However, to investigate the mechanism of miR-490-3p/AURKA on the proliferation, migration, and apoptosis of cancer cells, Si-AURKA and miR-490-3p inhibitor were transfected into RT4 and T24 cells." (PMID 34702201, 2021). "Several AURKA substrates exhibit multiple and counteracting functions in cancer development." (PMID 33451333, 2021). "Since AURKA promotes a chemoresistant cancer phenotype, we investigated whether TGF-β-induced chemoresistance was also dependent on AURKA expression." (PMID 33674749, 2021). "In addition to the identifiedCCNB2 in eleven pathways, a second gene -AURKA-included in the hub cancer signature genes, was also identified." (PMID 34455715, 2021). "Overexpression of AURKA is frequently detected in different human cancers." (PMID 34244565, 2021). "The high expression of AURKA has been seen in many sorts of cancers such as ovarian, liver, and colorectal ones making some oncogenic factors like c‐MYC, NF‐kB, and β‐catenin active, and it could lead to chromosomal instability." (PMID 34337875, 2021). "To date, a considerable number of reports have indicated AURKA in genomic instability and cancer." (PMID 34244565, 2021).
cancer (continued). "Compounds targeting AURKA, particularly alisertib, have been extensively studied in preclinical models, where they have shown synergistic effects with other targeted therapies, leading to tumor regression in a variety of cancer models." (PMID 34332577, 2021). "The expression level of AURKA gene in 13 common cancers increased significantly compared to normal." (PMID 34337875, 2021). "In fact, our results showed that the high level of AURKA might have an influence on the overall survival of many types of cancer patients like breast, kidney, liver, lung, prostate, and uterine." (PMID 34337875, 2021). "Abnormally upregulated AURKA in cancers is always stabilized by other molecules." (PMID 33451333, 2021). "Based on the molecular docking results, the top 9 compounds unraveled higher binding affinities than that of alisertib (MLN8237, Milennium Pharmaceuticals, Inc., Cambridge, MA), which is a highly selective AURKA small-molecule inhibitor developed for the treatment of malignancies." (PMID 32978717, 2021). "Either blocking the subcellular localization of AURKA or inhibiting protein–protein interactions could sensitize drug-resistant cancer cells to kinase inhibition." (PMID 34050264, 2021). "Moreover, previous studies have indicated that the overexpression of AURKA in some cancers such as stomach, bladder, and colorectal ones are in inverse relation to disease prognosis." (PMID 34337875, 2021). "Gene amplification, transcriptional activation and inhibition of protein degradation could contribute to the elevated levels of AURKA expression in cancer tissues." (PMID 33451333, 2021). "Therefore, the development of chemically or mechanistically diverse AURKA inhibitors is necessary to overcome current clinical challenges and will provide diverse options for using AURKA inhibitors in precision cancer medicine." (PMID 34050264, 2021). "The abnormal expression level of AURKA correlates with some factors which could develop cancer cells." (PMID 34337875, 2021). "Aurora A kinase (AURKA) is crucial in oncogenesis, because its overexpression or amplification may incline the development of various types of cancer, including MM." (PMID 32978717, 2021). "Since fine-tuned regulation of AURKA activity and expression is highly important in multiple central cellular processes, such as the G2/M transition and mitosis, dysregulation of its activity or expression plays an important role in cancer development." (PMID 34050264, 2021). "Indeed, up-regulation of AURKA in cancer cells also promotes its translocation to the nucleus, where it regulates the activity of transcription and splicing factors, resulting in modulation of gene expression programs." (PMID 34930366, 2021). "Recent studies showed that, the level of AURKA could be an independent prognostic factor for some types of cancers." (PMID 34337875, 2021). "Hence, the role of AURKA in cancer development and the therapeutic response deserves more attention and suggests the great potential of AURKA as a therapeutic target in cancer." (PMID 34050264, 2021). "AURKA is a key regulator of mitosis and a kinase that promotes cancer migration and invasion." (PMID 34053447, 2021). "AURKA inhibition or depletion inhibits apoptosis and attenuates tumor growth in many cancers." (PMID 33158056, 2020). "Thus, an alternative approach to regulate AURKA is to identify and modulate its downstream targets in different cancers." (PMID 33158056, 2020). "AURKA has been established as a legit oncogene and thus, a vital therapeutic target in cancer." (PMID 33245732, 2020). "The elevated expression of AURKA is frequently reported in many cancer types." (PMID 32851091, 2020). "As AURKA interacts with different oncogenic pathways to favor cell proliferation, survival, and therapeutic resistance, it can also mediate Myc oncogenic effects in cancers." (PMID 33167327, 2020).
cancer (continued). "However, AURKA is a key factor for T cell activation, which occurs mainly through the Lck signal and involves T cells in the immune reaction against cancer." (PMID 33050100, 2020). "Moreover, overexpression of AURKA-induced HCC metastasis is associated with epithelial-mesenchymal transition (EMT) and cancer stem cell (CSC) behaviors controlled by the PI3K/AKT pathway." (PMID 32775402, 2020). "Additionally, the upregulation of AURKA was related to the pathological stage, the expression levels of AURKA increased as the cancer stages increased." (PMID 32849824, 2020). "AURKA is yet another essential target for a better clinical outcome in cancer treatment." (PMID 32033228, 2020). "Recent investigation found that AURKA was involved in a variety of human cancers." (PMID 32849824, 2020). "To verify if the inhibition, at least of one of these hub genes, could affect all BC subtypes we performed functional studies choosing AURKA as a reference target switch for its known involvements in cancer development." (PMID 32932728, 2020). "Based on structural similarity with kinase inhibitors, we additionally performed a kinome screen to profile binding of APA and its acetylated product NAPA with respect to > 300 kinases, and identified differential binding to Aurora Kinase A (AURKA) which is a known drug target in cancer." (PMID 33384440, 2020). "In cancer, Aurora kinase A (AURKA) is overexpressed and involved in tumorigenesis by multiple mechanisms, such as phosphorylation of RAS-association domain family 1, to disrupt microtubules stabilization and cell cycle arrest, leading to unregulated proliferation." (PMID 33167327, 2020). "Increased expression or amplification of AURKA is common in most human cancers including BC." (PMID 33245732, 2020). "AURKA is a kinase involves in destabilizing the microtubules of cancer cells by phosphorylation of the tumor suppressor RAS-association domain family 1, isoform A (RASSF1A), and subsequently increases abnormal cancer cells proliferation by disrupting the mitotic phase." (PMID 32469983, 2020). "Previous studies indicated that miR-32 may be tumor suppressive in nature and its regulatory effect on AURKA have been shown in various cancer subtypes." (PMID 33245732, 2020). "The effect of AURKA on chemosensitivity has been studied in different cancer types." (PMID 32851091, 2020). "A new redox-sensitive micellar system consisting of hyaluronic acid (HA)-based amphiphilic conjugate (HA-ss-(OA-g-bPEI), HSOP) was formulated for tumor-based codelivery of paclitaxel (PTX) and AURKA-explicit siRNA (si-AURKA) for the treatment of targeted cancer therapy." (PMID 32521684, 2020). "Alisertib, an AURKA inhibitor, is currently undergoing clinical trials for various cancers, and it may be useful for the treatment of ACC in the future." (PMID 32287321, 2020). "AURKA protein plays a role in tumor development and progression of various cancers including BC." (PMID 32932728, 2020). "Using the AURKA(WT) and AURKA(V352I) transgenic zebrafish model, we could test the anti-cancer effect of multiple kinase inhibitors and combinational therapeutics." (PMID 31269749, 2019). "Aurora kinase A (AURKA) is frequently overexpressed in several cancers." (PMID 31740746, 2019). "Most of the analyzed samples stained positive for AURKA, and the increased expression correlated with the decreased overall and progression-free survival very well, which is consistent with previous studies in breast, gastric, ovarian, colon, and lung cancers." (PMID 31647033, 2019).
cancer (continued). "Since Aurora kinase A, which is associated with TPX2, is currently tested as a therapeutic target in cancer treatment, we investigated whether BRCA2-mutant cancer cells were more sensitive to chemical inhibition of Aurora-A." (PMID 30177840, 2019). "Aurora-A (AURKA) has been proven to be an oncogene in a variety of cancers; however, whether its expression relates to patient survival and the association with radiotherapy remains unclear in non-small cell lung cancer (NSCLC)." (PMID 31647033, 2019). "AURKA overexpression has been shown to mediate pro-tumorigenic functions in addition to mitosis, and drugs aimed at inhibiting its expression to improve anti-cancer therapy are currently under clinical trials." (PMID 30068336, 2018). "In GSE13507, high expression of AURKA in PBC was dramatically associated with tumor stage (χ2 = 11.815, P = 0.019), grade (χ2 = 17.927, P = 0.000), invasiveness (χ2 = 13.229, P = 0.001), and cancer-specific survival (χ2 = 4.557, P = 0.042)." (PMID 30547784, 2018). "The down-regulation of the proto-oncogene AURKA inhibited the expression of tiRNALeu in cancer cells, suggesting that tiRNALeu might play a part in promoting the proliferation of cancer cells by regulating the expression of AURKA." (PMID 29743091, 2018). "The roles of AURKA outside of mitosis, and how these might contribute to cancer progression, are not well understood." (PMID 29899121, 2018). "Current drugs that aim to treat cancer by blocking the activity of AURKA show poor results." (PMID 30070631, 2018). "Targeting mitochondrial hyperfunctionality together with AURKA inhibition might therefore represent an innovative approach in the development of anti-cancer treatments." (PMID 30070631, 2018). "AURKA also mediates Myc (N-Myc, c-Myc, L-Myc) oncogenic effects in cancers." (PMID 28147341, 2017). "Together, our study reveals a previously unknown function of AURKA in controlling collective invasion process, which might provide a promising strategy for overcoming cancer metastasis." (PMID 28592839, 2017). "Furthermore, overexpression of AURKA mediated resistance to gefitinib, taxol and cisplatin in cancer cells." (PMID 28183295, 2017). "Taken together, activation of AURKA–eIF4E axis in cancer cells could play a crucial role for resistance to several chemotherapeutics." (PMID 28417568, 2017). "Loss of SMARCA4 is necessary for this hypersensitivity, but as re-expressing SMARCA4 in a cancer cell line lacking it only partially rescued cells from AURKA knockdown, SMARCA4 loss is not sufficient for this sensitivity." (PMID 28102363, 2017). "Therefore, our results add to the current knowledge and suggest a multifaceted regulation of c‐MYC at different levels by AURKA in cancer." (PMID 28417568, 2017). "Moreover, this protein-protein interaction network also indicated that HNRNPK was physically interacted with many other critical cancer associated genes such as EGFR, CD81 and AURKA." (PMID 29262567, 2017). "Aurora kinase A (AURKA), a serine/threonine kinase is overexpressed in many cancer types." (PMID 29050357, 2017). "We analyzed correlation between AurkA expression and tumorigenic properties of cancer cells." (PMID 27341528, 2016). "AurkA overexpression/amplification was found in several human cancers." (PMID 27341528, 2016). "Targeting this interaction in G1 cells to perturb centrosome clustering in cancer-like conditions in which AURKA is overexpressed and it induces resistance to apoptosis could be a promising strategy to restore cell death." (PMID 27624869, 2016).